TNF (tumor necrosis factor)
Diseases named in the same sentence as TNF in open-access papers (continued):
Sharing a sentence is not in itself a finding about the gene and the disease.
periodontitis (continued). "The aim of this study was to investigate the relationship between the severity of apical periodontitis (AP) and chronic periodontitis (CP) and serum (s) TNF-α, IL-10, PGE2 and NO levels, as well as PGE2 and NO levels in gingival crevicular fluid (GCF) samples." (PMID 38795217, 2024). "Among the many immunological mediators secreted during inflammatory processes, several pro‐inflammatory interleukins (IL‐1, IL‐6, IL‐8) and tumor necrosis factor‐alpha (TNF‐α) have been extensively studied for their possible systemic presence in periodontitis." (PMID 39494478, 2024). "Numerous studies have highlighted an important role of TNF in the pathogenesis of chronic periodontitis." (PMID 39253090, 2024). "Suppression of the inflammatory response is one of the guidelines for the treatment of periodontitis; IL-1β and TNF-α are two pro-inflammatory cytokines active in periodontitis." (PMID 39445594, 2024). "The TNF-α levels also differed significantly from the positive control group, which consisted of rats induced with periodontitis and treated with 0.2 % CHX (p < 0.05)." (PMID 39539670, 2024). "A cascade of inflammatory proteins and enzymes is directly involved in periodontitis’ osteoclastogenesis, including proinflammatory cytokines such as IL-1β, IL-6, IL-11, IL-17, and TNF-α (point 6)." (PMID 38792574, 2024). "Cytokines, such as IL-1β, IL-6 and TNF-α, activate inflammation-related transcription factors or activate related signaling pathways, thereby accelerating the process of periodontitis." (PMID 38178140, 2024). "Augmented levels of TNF protein were detected in chronic apical periodontitis lesions by immunohistochemistry, particularly in older patients, suggesting local induction of TNF levels during periodontitis." (PMID 39253090, 2024). "In experimental periodontitis, the systemic levels of IL-1beta and TNF were upregulated upon periodontal infection indicating periodontitis-induced systemic inflammation." (PMID 39253090, 2024). "The application of EV therapy in periodontitis presents significant clinical opportunities by demonstrating how EVs can influence key cytokines like IL-5, IL-6, IL-17A, IL-10, and TNF-α." (PMID 38891939, 2024). "The quantification of the level of these inflammatory mediators in the gingival crevicular fluid (GCF) suggests that IL-6, interleukin-8 (IL-8), and TNF-α have been reported as relevant biomarkers in the pathophysiology of periodontitis." (PMID 38196480, 2024). "The systemic inflammatory–oxidative effects of periodontitis and MetS were biochemically evaluated using the serum TNF-α level, IL-1β/IL-10 ratio, and oxidative stress index (OSI: TOS/TAS)." (PMID 39590401, 2024). "Patients with periodontitis have higher values of white blood cells, interleukin (IL)-1, IL-6, tumor necrosis factor (TNF)-α and C-reactive protein (CRP)." (PMID 38573898, 2024). "TNF-α, a key cytokine produced in response to periodontal pathogens, plays a crucial role in periodontitis by promoting osteoclast formation and thus contributing to alveolar bone and connective tissue degradation." (PMID 38843124, 2024). "In the present study, elevated levels of IL-1β, IL-6, and TNF-α were observed in the periodontitis group, indicating an inflammatory response mediated by inflammatory cells during disease progression." (PMID 38919285, 2024). "Previous studies conducted by our group observed that animals induced with periodontitis showed an increase in IL‐1 and TNF‐α expression." (PMID 39497351, 2024). "Our findings indicate that as periodontitis progresses, there is a notable increase in cytokines 1β, 8 and tumor necrosis factor-α." (PMID 38920850, 2024). "In detail, M1 macrophages mainly take part in the destructive process of periodontitis by evoking secretion of diverse pro-inflammatory factors, such as interleukin-6 (IL-6), tumor necrosis factor-α (TNF-α) and inducible nitric oxide synthase (iNOS)." (PMID 38689292, 2024).
periodontitis (continued). "On the other hand, there have been very few studies on the possible effects of TNF-α inhibition on periodontitis." (PMID 38256582, 2024). "The body responds to periodontitis by producing inflammatory cytokines like TNF-α, IL-1β, and IL-6, which play crucial roles in the disease's progression." (PMID 39044527, 2024). "We evaluated the effects of ω-3 PUFA on the cytokines TNFα, IL-2, IFNγ, IL-4, and IL-5 in a P. gingivalis ligature-induced periodontitis in the serum of mice." (PMID 37378834, 2024). "In experimental models of periodontitis, TNF and the IL-23/IL-17 axis play a pivotal role in disease pathogenesis." (PMID 39253090, 2024). "Consistently, we detected higher expression levels of TNF-α and IL-6 in periodontitis tissues and ELISA results showed higher concentration of TNF-α and IL-6 in serum." (PMID 38319542, 2024). "It has been suggested that IL-6 activates pro-inflammatory immune circuits in periodontitis by activating innate and adaptive immune cells and by favoring bone resorption together with IL-1 and TNF." (PMID 39253090, 2024). "IL-6 levels in AD patients were substantially higher than in controls, and periodontitis patients had noticeably higher TNF-a levels than AD patients with healthy periodontium." (PMID 38230738, 2024). "The important role of inflammatory bimarkers, such as cortisol, TGF-1β and TNF-α, in the pathogenesis of periodontitis has drawn the attention to the systemic impact of periodontitis and its potential relationship with other diseases." (PMID 38711116, 2024). "The levels of a broad variety of biomolecules and numerous proinflammatory cytokines that contribute to the disease, such as interleukin (IL-1β and IL-6) and tumor necrosis factor (TNFα), have been reported to be raised in patients with periodontitis." (PMID 38535279, 2024). "Unexpectedly, GCF IL-1β and TNF-α levels were higher in T1DM periodontitis patients compared to T2DM periodontitis ones." (PMID 39000406, 2024). "Based on the studies above, we found that cytokines (especially TNF-α) play a critical role in the occurrence and development of periodontitis and dyslipidemia." (PMID 38684998, 2024). "Immunohistochemical staining demonstrated that the periodontitis group showed increased expression of the inflammatory marker (TNFα), along with decreased levels of AFF4 and osteogenic protein (RUNX2, COL1A1)." (PMID 37731335, 2024). "For instance, studies on green tea extract (Camellia sinensis) have demonstrated its ability to reduce levels of proinflammatory cytokines such as TNF-α and IL-1β in periodontitis models." (PMID 39539670, 2024). "For example, it was shown that HDAC3 significantly reduced the expression of inflammatory mediators in gingival fibroblasts (GFs) from both healthy and diseased individuals in a model of periodontitis induced by TNF-α and Porphyromonas gingivalis." (PMID 39830512, 2024). "Patients with severe periodontitis exhibit significant increases in the expression of interleukin-1β (IL-1β), tumor necrosis factor-α (TNF-α), nod-like receptor protein 3 (NLRP3), and their absence in melanoma 2 (AIM2) inflammasomes in the gingival tissues." (PMID 38921772, 2024). "There also appeared to be a positive correlation between miR-223 levels and disease severity, as determined by increased TNF-α and clinical parameters in the chronic periodontitis group compared to healthy controls." (PMID 39125843, 2024). "In a recent intervention study in PD, application of photodynamic therapy resulted in significant improvement in the clinical parameters of periodontitis and immunological biomarkers IL-6 and TNF-α in PD patients with severe periodontitis." (PMID 38674088, 2024). "Patients with AD and periodontitis had elevated serum levels of TNF-α and antibodies to P. gingivalis, A. actinomycetemcomitans and T. forsythia." (PMID 39064809, 2024).
periodontitis (continued). "GF and periodontal ligament fibroblasts facilitate the inflammatory cascade in periodontitis, producing pro-inflammatory cytokines, like IL-1β, IL-6 and TNF-α." (PMID 39252697, 2024). "Another study found that chemerin and inflammatory cytokines such as IL‐1β, IL‐6, and TNF‐α were notably higher in the serum of patients with chronic periodontitis than those in the control group, (periodontally healthy/gingivitis)." (PMID 39494478, 2024). "Chronic periodontitis patients show an increase in the TNF-α, IL-6, IL-1B, and RANK-L levels and a decrease in OPG." (PMID 38817441, 2024). "such as the IL-17 and TNF signaling pathways, highlights their potential role in exacerbating the inflammatory environment in periodontitis." (PMID 39717623, 2024). "Etanercept treatment reduced neutrophil recruitment, ameliorated the degree of inflammation in periodontitis and reduced local tissue injury suggesting that TNF drives local inflammation and tissue injury in periodontitis." (PMID 39253090, 2024). "The second mechanism is mediated by inflammatory cytokines produced during periodontitis, including tumor necrosis factor (TNF), interleukin-1β (IL-1β), and IL-6." (PMID 39851378, 2024). "One study reported increased serum levels of IFN-gamma, TNF, and IL-10 in patients with periodontitis as compared to healthy controls." (PMID 39253090, 2024). "The results showed that the targets of CR in the treatment of periodontitis mainly involved the IL-17 signaling pathway, the TNF signaling pathway and the Relaxin signaling pathway." (PMID 38704553, 2024). "Plasma levels of TNF-α and PGE2 were found to be elevated in women with periodontitis compared to periodontally healthy women, while pregnant women with periodontitis showed elevated plasma levels of TNF-α, IL-4, and IL-6." (PMID 38672972, 2024). "TNFα is also tricky to classify, due to the difficulty in setting benchmark levels, as smaller TNFα concentrations are recognized in peri-implantitis than medium-grade periodontitis." (PMID 37232785, 2023). "Elevated levels of IL‐1β, IL‐6, and TNF‐α have been detected in inflamed gingival tissues of patients with periodontitis, which contributes to tissue destruction and the progress of periodontitis." (PMID 37506160, 2023). "It exhibits a number of direct actions in periodontal tissues, such as stimulating immune response cells to synthesize other cytokines (interleukin-6, interleukin-8, TNF and G-CSF) that are involved in the development of periodontitis." (PMID 37510729, 2023). "During inflammatory conditions, such as periodontitis, TNF levels increase in the gingival crevicular fluid to promote the degeneration of inflamed periodontal tissues." (PMID 36845132, 2023). "Here, we selected anti-inflammatory probiotics Lactobacillus pentosus NK357 and Bifidobacterium bifidum NK391, which inhibited TNF-α expression in PG-treated macrophages, and investigated their effects on PG-induced periodontitis and CI in mice." (PMID 36904068, 2023). "It has been reported that resistin acts as a proinflammatory molecule by stimulating the secretion of tumor necrosis factor α (TNF-α), interleukin (IL)-6 and IL-12, thereby inducing its own production via a positive feedback cycle during periodontitis." (PMID 38149100, 2023). "While this time frame allowed us to observe significant changes in TNF-α expression, further research is needed to investigate the progression of periodontitis over shorter or longer periods." (PMID 37232780, 2023). "BBR effectively reduced local and systemic inflammation in a periodontitis rat model by lowering TNF-α and IL-17 production and the number of IL-17A+ cells in the alveolar bone." (PMID 37317243, 2023). "The combination of NK357 with NK391 (NKc) additively decreased PG 16S rDNA levels as well as suppressed PG-induced periodontitis: they suppressed TNF-α and IL-6 expression and GP+LPS+ and NF-κB+CD11c cell populations in the periodontal tissue." (PMID 36904068, 2023).
periodontitis (continued). "Periodontitis elevates the levels of inflammatory cytokines like interleukin-6 (IL-6), interleukin-1 (IL-1), and tumor necrosis factor alpha (TNF-α)." (PMID 38132215, 2023). "Initially, to ensure the reliability of the samples, inflammatory cytokines including IL-1β, IL-6, and TNF-α of each group were evaluated by RT-qPCR, all of which are significantly upregulated in periodontitis." (PMID 37261283, 2023). "High levels of pro-inflammatory cytokines such as TNFα, IL-6, IL-1, and IL-17 are present in the milieu of both periodontitis and SSc." (PMID 36899985, 2023). "The principal component from P.g is lipopolysaccharide (LPS), which is important virulence factor in the mechanisms of periodontitis and can induce TNF-α secretion." (PMID 37232780, 2023). "Among the many pro-inflammatory cytokines that macrophage mediate, tumor necrosis factor α (TNF-α) is one of the key early cytokines induced by periodontal pathogens in destructive periodontitis." (PMID 37232780, 2023). "We also confirmed that DMWE inhibited the increased concentrations of TNF-α and IL-6 in the serum of periodontitis-induced rats in a dose-dependent manner." (PMID 36677905, 2023). "Several in-vivo and in-vitro studies of periodontitis have shown that the nervous and immune systems respond to systemic inflammatory responses, increasing interleukin-1, C-reactive protein, tumor necrosis factor, and matrix metalloproteinases." (PMID 37113482, 2023). "Individuals with periodontitis have elevated circulatory levels of pro-inflammatory cytokines, such as IL-1, IL-6, and TNF-alpha." (PMID 38029267, 2023). "In periodontitis, various proinflammatory cytokines such as IL‐1β, IL‐6, and tumor necrosis factor‐α (TNF‐α) are produced." (PMID 37506160, 2023). "The TNF-α plasma levels were slightly higher after the induction of periodontitis (18.7 ng/mL, SD ± 5.293) compared with phase 1 (16.67 ng/mL, SD ± 3.509)." (PMID 36840029, 2023). "Macrophages express a variety of inflammatory cytokines, including TNF-α, IL-1β, and IL-6 in periodontitis-affected sites." (PMID 37626627, 2023). "TNF-α production, induced by lipopolysaccharide release in periodontitis, significantly inhibits osteogenic differentiation of periodontal ligament stem cells, resulting in the loss of periodontal tissue regenerative capacity." (PMID 37981679, 2023). "Given the dual functions of TNF-α as an inflammatory mediator, these findings show that there is still a discrepancy in the determination of the levels of TNF-α in patients with periodontitis associated with OSA." (PMID 36967976, 2023). "This study aims to compare the salivary and gingival crevicular fluid (GCF) concentrations of five cytokines: IL-1β, IL-6, IL-17A, IL-33, and Tumor Necrosis Factor-alpha (TNF-α) in patients with OSA and their association with periodontitis." (PMID 36967976, 2023). "(p < 0.05) Tumor Necrosis Factor-α and Interleukin-1β levels that were high in the gingiva of the rats with periodontitis were found significantly lower in rats administered celastrol." (PMID 38532834, 2023). "Alternatively, in patients with chronic periodontitis and chronic systemic diseases, higher levels of inflammatory cytokines are observed, including TNF-α, IL-1, and IL-6." (PMID 37481511, 2023). "Some studies have found a significant reduction in serum levels of tumor necrosis factor (TNF) and interleukin IL-1 (two critical biomarkers of periodontitis) in people with chronic periodontitis after consuming tomato drinks for a certain time." (PMID 37600299, 2023). "Related research reported that stem cells from human exfoliated deciduous teeth (SHED)-derived CEVs (SHED-EVs) reduced IL-6 and TNF-α expression in lipopolysaccharide (LPS)-induced inflammatory BMMSCs, and in tissues from the defect area of periodontitis mice." (PMID 36982864, 2023). "The results of this study demonstrate cytokine dynamics of IL-1β, TNF-α, and IL-10 in periodontitis, especially in older people." (PMID 37623272, 2023).
periodontitis (continued). "In the periodontitis mice treated with synthetic (+)-terrein, the serum TNF-α levels were significantly reduced down to the uninduced periodontitis level (p = 0.02)." (PMID 36983482, 2023). "The association between AS and periodontal diseases is supported by the detection of pronounced increases in serum interleukin (IL)-6 and tumor necrosis factor-alpha (TNF-α) levels between the immunopathological state in AS and periodontitis." (PMID 37875827, 2023). "The upregulation of IL-1β and TNF-α levels in the gums of aged mice and Pg-injected mice led us to next delineate the roles of these two cytokines in the pathogenesis of periodontitis and AD." (PMID 36915108, 2023). "DM1 patients with periodontitis showed higher fibrinogen (371.3 ± 114.7, p < 0.01) and TNF-α (1.6 ± 1.2, p < 0.001) concentrations, as well as lower OHI (2.1 ± 0.7, p < 0.001) and a lower number of teeth (p < 0.001)." (PMID 36769794, 2023). "TNF‐α is crucial to the initiation and perpetuation of inflammatory and tissue‐destructive responses in periodontitis." (PMID 36894516, 2023). "In our present study, we focused on Wnt pathway activation and its relationship with TNF-α, a key pro-inflammatory cytokine in periodontitis." (PMID 37232780, 2023). "Accordingly, it is reasonable to hypothesize that the consistent expression of activated β-catenin and TNF-α is associated with macrophages, and that the activation of the Wnt pathway is linked to the recruitment and activation of macrophages in the gingiva during periodontitis." (PMID 37232780, 2023). "It was reported that the expression of tumour necrosis factor-alpha (TNF-α) generally suppresses osteogenesis and increases among the various chronic inflammatory bone diseases, such as chronic periodontitis." (PMID 37244994, 2023). "Periodontitis triggers a systemic inflammatory response mediated by various factors, including C-reactive protein, interleukin 1b (IL-1b), interleukin 6 (IL-6), tumor necrosis factor alpha (TNF-α), and others." (PMID 38001437, 2023). "Chronic periodontitis promotes the release of protein C-reactive protein, interleukin-1b and interleukin-6, and Tumor Necrosis Factor-alpha by neutrophils, which stimulate bone resorption and consequent destruction of periodontal tissue." (PMID 37297629, 2023). "TNF-α and caspase-1 salivary levels were higher in periodontitis patients than in healthy controls and were positively correlated with all clinical parameters." (PMID 36794778, 2023). "A clinical study has reported significantly higher levels of IL-1β and TNF-α in the gingival crevicular fluid of individuals with periodontitis and peri-implantitis compared to both healthy subjects and those with healthy implants." (PMID 37626627, 2023). "Both periodontitis and colon cancer have been associated with elevated MDSC levels, and increased levels of TNF-α, IL-1β, IL-6 and MMP-9 are also common factors in both conditions." (PMID 38029267, 2023). "Based on the literature data available, we aimed to delineate the roles of IL-1β and TNF-α in the pathogenesis of periodontitis and AD." (PMID 36915108, 2023). "Oral treatment of patients with chronic periodontitis with tablets containing probiotic strain of L. reuteri induced a significant reduction in TNFα, IL‐1β, and IL‐17 levels." (PMID 37206247, 2023). "More specifically, TNF-α expression levels in the gingival tissue and serum of patients with periodontitis are higher than those of the healthy control group." (PMID 37244994, 2023). "This study aimed to clinically analyze the periodontal status and cytokine levels of IL-1β, TNF-α, and IL-10 in older people and adults with periodontitis." (PMID 37623272, 2023). "This has demonstrated that subjects with gingivitis and periodontitis present a significant increase in the levels of IL-6 and other cytokines involved in the inflammatory response, such as IL-1β and TNF-α, compared to periodontally healthy subjects." (PMID 36770741, 2023).